SNORD116-13 (small nucleolar RNA, C/D box 116-13)
Synonyms: HBII-85-13
Gene: Small nucleolar RNA gene on chromosome 15 (25,079,058 to 25,079,149, forward strand). Ensembl gene ENSG00000207137.
Gene Ontology:
Biological process: RNA processing
Cellular component: nucleolus
Homologues: Orthologues: chimpanzee SNORD116 (98% identical), macaque SNORD116 (93% identical), guinea pig SNORD116 (80% identical). Paralogues in human: SNORD116-24 (89% identical), SNORD116-16 (88% identical), SNORD116-20 (88% identical), SNORD116-12 (87% identical), SNORD116-17 (87% identical), SNORD116-19 (87% identical), SNORD116-14 (86% identical), SNORD116-15 (86% identical), SNORD116-18 (86% identical), SNORD116-21 (86% identical), SNORD116-22 (86% identical), SNORD116-23 (85% identical), and 20 more.